SYP (synaptophysin)
Diseases named in the same sentence as SYP in open-access papers (continued):
Sharing a sentence is not in itself a finding about the gene and the disease.
lymphoma (13 papers, 2005 to 2025). A malignant (clonal) proliferation of B- lymphocytes or T- lymphocytes which involves the lymph nodes, bone marrow and/or extranodal sites. "A broad panel of immunohistochemistry excluded lymphoma and nephroblastoma, confirming extra-adrenal paraganglioma based on strong positivity for anti-synaptophysin, neuron-specific enolase, chromogranin A, and cytokeratin 19 antibodies." (PMID 40948633, 2025). "For example, in ALCL, when it is challenging to diagnose CD30-positive lymphoma or differentiate it from activated immunoblasts, synaptophysin staining may be helpful." (PMID 36401284, 2022). "To date, synaptophysin expression has not been reported in normal immune cells, and its overexpression in hematologic malignancies, including lymphoma, has not been reported, except in one case of chronic lymphoblastic leukemia/small lymphocytic lymphoma." (PMID 36401284, 2022). "Our literature search did not reveal synaptophysin positivity in any case of lymphoma or leukemia." (PMID 19284608, 2009). "Other unusual circumstances contributing to misinterpretation include a include a synaptophysin, chromogranin and CD56 (keratin, desmin and WT1 negative) mesenteric ES (EWSR1-FLI1 positive) and numerous tumor-associated lymphocytes in an ELS originally diagnosed as lymphoma." (PMID 34698236, 2021). "Immunohistochemistry staining showed positivity for NSE, synaptophysin, chromogranin A, CD56, S100 protein neurofilaments, calretinin, and glial fibrillary acidic protein and was negative for epithelial and lymphoma markers." (PMID 40821301, 2025).
pancreatic neuroendocrine tumor (13 papers, 2013 to 2025). Pancreatic endocrine tumor, also known as pancreatic neuroendocrine tumor (PNET), describes a group of endocrine tumors originating in the pancreas that are usually indolent and benign, but may have the potential to be malignant. "CHGA and SYP are regarded as markers of NE differentiation structurally linked to cytoplasmic granules and vesicles and are, as a rule, simultaneously expressed in typical NETs of different organs such as pheocromocytomas, intestinal and lung carcinoids and pancreatic NETs." (PMID 24277232, 2014). "The tumor manifested several features that were consistent with pancreatic neuroendocrine tumors (panNETs), such as organoid structures with trabecular and cribriform patterns, and the expression of chromogranin A and synaptophysin." (PMID 26192435, 2015). "Tumor cells for pancreatic neuroendocrine tumors stain positively for chromogranin and synaptophysin." (PMID 24348574, 2013). "Liver biopsy was benign, while endoscopic ultrasound-guided biopsy of the pancreatic mass showed a well-differentiated, WHO grade 1 pancreatic neuroendocrine tumor (NET) positive for chromogranin, synaptophysin, and CD56, with Ki-67 < 3%." (PMID 41510403, 2025). "The CD56 expression, synaptophysin, and chromogranin have been reported in SPNP and can overlap with predicted expression in pancreatic NETs." (PMID 38169685, 2023). "The tumor of the prostate is diffusely positive for NKX3.1 (a prostate marker) and displays single-cell nuclear positivity for synaptophysin, but negativity for VIP and Islet‐1, a marker for pancreatic neuroendocrine tumors (PanNET)." (PMID 33398457, 2021). "Cells from SPTs may also reveal focal immunoreactivity for cytokeratin and synaptophysin, demonstrate abnormal nuclear localization of β-catenin and the presence of progesterone receptors and may express galectin-3, all of which are useful in differentiating SPTs from endocrine pancreatic tumors." (PMID 23384084, 2013). "Histopathological and immunohistochemical results diagnosed well-differentiated pancreatic neuroendocrine tumor grade II (NETG2) with liver metastases and no spleen invasion, with the presence of diffuse positive chromogranin A and synaptophysin." (PMID 27928440, 2016). "Case report: We presented the case of 59-year-old patient, diagnosed with non-functional well-differentiated pancreatic neuroendocrine tumor grade II (NET G2) with the presence of chromogranin A, synaptophysin and somatostatin receptor 2, together with liver and bone metastases." (PMID 27928440, 2016).
Parkinson disease (13 papers, 2012 to 2025). A progressive degenerative disorder of the central nervous system characterized by loss of dopamine producing neurons in the substantia nigra and the presence of Lewy bodies in the substantia nigra and locus coeruleus. "Proteomic analyses have identified changes in protein expression associated with Parkinson’s disease, including synaptic proteins like Synapsin I and Synaptophysin, and alterations in autophagy-related proteins." (PMID 40469842, 2025). "Reduced synaptophysin protein levels have been implicated in AD, Parkinson’s disease, and frontotemporal dementia." (PMID 37175376, 2023). "In agreement with our observation, fluorescence analysis of Parkinson’s disease and control brains showed that synaptophysin was reduced in the striatum of Parkinson’s disease brain, compared to controls." (PMID 32641150, 2020). "We also noted that fluorescence intensity of synaptophysin in striatum of mice injected with Parkinson’s disease RBC-EVs was reduced by ~ 50% when compared to control RBC-EV-injected mice." (PMID 32641150, 2020). "Conditions of most concern are insomnia and REM sleep behavior disorder, a type of abnormal sleep considered to be the precursor to α-synaptophysin disease, such as Parkinson’s disease; such disordered sleep affects more than 50% of patients with Parkinson’s disease." (PMID 36819721, 2023). "In Alzheimer’s and Parkinson’s diseases, the levels of brain-derived neurotrophic factor (BDNF), synaptophysin (SYN), and nerve growth factor (NGF) are reduced, leading to impaired synaptic plasticity as well as decreased neuronal density and cholinergic neuron survival in the hippocampus." (PMID 41375975, 2025).
epilepsy (12 papers, 2012 to 2025). A brain disorder characterized by episodes of abnormally increased neuronal discharge resulting in transient episodes of sensory or motor neurological dysfunction, or psychic dysfunction. "We recently identified a male patient with severe intellectual disability, hypotonia, epilepsy and callosal agenesis who has a point mutation in the juxtamembrane region of the fourth transmembrane domain of synaptophysin (T198I)." (PMID 28887151, 2017). "A novel mutation in the SYP gene was identified in a male patient with severe ID, hypotonia, epilepsy, hypogonadotropic hypogonadism and callosal agenesis." (PMID 28887151, 2017). "The enhanced expression of PSD-95 and synaptophysin (SYN) in n-3 PUFA supplementation groups compared with n-3 PUFA-deficient groups suggests that viable dendritic spines are functional for brain homeostasis in PTZ-induced epilepsy." (PMID 37367679, 2023). "In addition, the SYP gene was also duplicated at Xp11.23 and is an integral membrane protein that regulates synaptic vesicle endocytosis associated with X-linked intellectual disability and epilepsy." (PMID 25400949, 2014). "In this study, we aimed to reveal the mechanism of cytoskeletal proteins in epilepsy by analyzing the levels of cytoskeletal proteins and SYP during seizures in mice intraperitoneally injected with kainic acid (KA)." (PMID 37070078, 2023). "In addition, synaptophysin (SYP) has been demonstrated to be a biomarker of synaptic transmission and synaptic reconstruction, which can trigger synaptic remodeling during epilepsy." (PMID 37070078, 2023). "Therefore, this study aimed to reveal the mechanism of cytoskeletal proteins in epilepsy by investigating the expression of cytoskeletal proteins and synaptophysin (SYP) in mice at 0, 3, 6, and 24 h, 3 days, and 7 days in a kainic acid (KA)-induced epileptic model." (PMID 37070078, 2023). "Clinicopathologic correlations showed an association of reduced synaptophysin labeling in the VL (subnucleus) in patients with TLE (p < 0.05) and lower neuronal density on CV in the AV in both TLE and partial epilepsy syndromes compared to other epilepsy cases (p < 0.01)." (PMID 24138281, 2013). "The signals of synaptophysin and GlyRα1 (mAb2b) did not co-localize with the human IgG from epilepsy patients in the white matter, indicating that staining in these areas was not caused by GlyR-specific aAb (patients 10–12)." (PMID 40739585, 2025). "We first investigated levels of the presynaptic marker synaptophysin, the excitatory postsynaptic marker PSD95 and the inhibitory postsynaptic marker gephyrin in hippocampus and temporal lobe samples at SE, LP and SRS stages of epilepsy." (PMID 31356824, 2019). "There were no significant changes in synaptophysin in the hippocampus or temporal lobe at any stage of epilepsy." (PMID 31356824, 2019). "In no epilepsy cases, with CV, synaptophysin, or GFAP did we identify distinct atrophy or sclerosis of a nucleus comparable to the degree of hippocampal damage in CHS." (PMID 24138281, 2013). "Comparing CHS (ILAE type 1), atypical HS patterns (ILAE types 2 and 3), and No-HS epilepsy patients, lower values for synaptophysin labeling were noted ipsilateral to CHS in all thalamic nuclei, although these differences were not significant." (PMID 24138281, 2013).
lung carcinoma (12 papers, 2015 to 2026). "On the basis of the Japan Lung Cancer Society Guidelines, pathological diagnosis using NE markers such as chromogranin A, synaptophysin, and NCAM/CD56 are currently used to distinguish SCLC from other lung NE tumors in Japan." (PMID 41220940, 2025). "This study evaluates the efficacy of a minimal panel immunostaining technique using immunohistochemical markers like napsin A, thyroid transcription factor 1 (TTF-1), p63, and synaptophysin to improve the precision of lung carcinoma subclassification." (PMID 39070322, 2024). "The Adeno-DKO mice developed SYP+ NE-like lung cancer at approximately 90 days and eventually died at around 250 days after the administration of Adeno-Cre viruses." (PMID 38099497, 2023). "For example, an IHC panel that includes thyroid transcription factor-1 (TTF-1), Napsin A, CK5/6, p40, CD56, synaptophysin (Syn), and chromogranin (CgA) will be useful in the differentiation of the histological type of lung cancers." (PMID 34975346, 2021). "Additionally, a minimal panel of immunohistochemical markers, including napsin A, TTF-1, p63, and synaptophysin, was used to subclassify lung carcinomas." (PMID 39070322, 2024). "In contrast, most tuft cell-like lung cancers were negative for the highly specific neuroendocrine markers, chromogranin A and synaptophysin, and TTF1, a marker of pulmonary adenocarcinoma and SCLC." (PMID 36402755, 2022). "In order to directly identify candidate mediators that are relevant to both lung cancer tumorigenesis and patient survival, we began with genes displaying significant correlation with mRNA levels of LMO1 and neuroendocrine markers CHGA, SYP and ENO2 levels in the MDACC dataset." (PMID 30038707, 2018). "To further evaluate the association of LMO1 expression with neuroendocrine differentiation in lung cancer cells, we examined the correlation between LMO1 mRNA levels and mRNA levels of neuroendocrine markers, including chromogranin A (CHGA), synaptophysin (SYP) and neuron-specific enolase-2 (ENO2)." (PMID 30038707, 2018).
medulloblastoma (11 papers, 2014 to 2025). A malignant, invasive embryonal neoplasm arising from the cerebellum. "These medulloblastoma-like tissues were confirmed to be strongly positive for medulloblastoma markers, such as βIII tubulin (Tuj1), synaptophysin, and Ki67." (PMID 35618979, 2022). "Histological analysis revealed an embryonal neoplasm with anaplastic features and immunopositive for synaptophysin, a neuronal marker characteristic of human medulloblastoma, and for FLAG-tagged MYCN." (PMID 31204176, 2019). "Western blot analysis showed the protein levels of GFAP and synaptophysin were comparable in medulloblastoma in these three groups of mice." (PMID 27802424, 2016). "Accordingly, the neuronal marker SYP is lost from the cerebellar nodules of aged Ptch1Δ/+Pn-1Δ/+ mice, while its expression is increased in end-stage Ptch1Δ/+ medulloblastomas." (PMID 25901736, 2015). "The majority of medulloblastomas exhibit neuronal differentiation in the form of immunoreactivity to synaptophysin and some also display focal glial differentiation (Glial fibrillary acidic protein (GFAP) immunopositivity)." (PMID 25101241, 2014). "Moreover, histologically, they all showed strong immunostaining for synaptophysin, which is one of the commonest stains used for the diagnosis of medulloblastoma in pathology practice." (PMID 38201659, 2024). "Desmoplastic medulloblastomas also comprise small round blue tumor cells, but typically harbor reticulin-free “pale islands” within a reticulin-rich stroma, which are often immunopositive for synaptophysin indicating neuronal differentiation." (PMID 25101241, 2014). "Apart from ETMR, the mimics of medulloblastoma do not usually express neuronal markers such as synaptophysin." (PMID 38201659, 2024). "Immunohistochemistry (IHC) for glial fibrillary acidic protein (GFAP) and synaptophysin showed that the expression pattern of both GFAP and synaptophysin in medulloblastoma in both Ptch1+/−; Gadd34+/− mice and Ptch1+/−;Gadd34−/− mice was comparable with Ptch1+/−; Gadd34+/+ mice." (PMID 27802424, 2016). "The synaptic vesicle protein Synaptophysin (SYP) and the microtubule-associated protein MAP2 are both expressed in Ptch1Δ/+ medulloblastomas, but not in the cerebellar nodules of aged Ptch1Δ/+Pn-1Δ/+ mice." (PMID 25901736, 2015).
neurocytomas (10 papers, 2014 to 2025). "Immunostaining of synaptophysin (a neuronal marker) is one of the essential diagnostic criteria for neurocytoma, but it lacks specificity as it is also reported in pilocytic astrocytoma, oligodendroglioma, and DNET." (PMID 35885538, 2022). "Immunohistochemical staining was positive for synaptophysin, neuronal nuclear antigen, and glial fibrillary acidic protein, consistent with the diagnosis of central neurocytoma." (PMID 39958057, 2025). "Histopathological analysis following a stereotactic biopsy confirmed the diagnosis of central neurocytoma, with immunohistochemistry showing positivity for synaptophysin and neuronal nuclear antigen." (PMID 39958057, 2025). "Particularly, neurocytomas show a high positivity for neural markers such as synaptophysin and NeuN." (PMID 40677455, 2025). "The small, uniform cells with neuronal differentiation observed in our patient’s tumor, coupled with immunohistochemical positivity for synaptophysin and NeuN, are consistent with the defining features of central neurocytoma." (PMID 39958057, 2025). "In pathology, extraventricular neurocytomas are diffusely positive for synaptophysin and exhibit variable neuronal nuclear antigen expression, neuronal differentiation markers." (PMID 39156001, 2024). "The round neoplastic cells in central neurocytoma show immunostaining evidence of neuronal differentiation, most commonly by the diffuse synaptophysin immunostaining." (PMID 35885538, 2022). "Immunohistochemistry confirmed that neurocytomas are positive for neuronal differentiation markers such as synaptophysin and chromogranin A and variable neurofilaments, NeuN and calretinin." (PMID 35663322, 2022). "All oligodendroglioma cases were immunopositive for IDH1-R132H immunostains, the three cases of central neurocytoma were immunopositive for synaptophysin, and the three cases of ependymoma showed at least focal dot-like cytoplasmic immunopositivity for EMA." (PMID 35885538, 2022). "In all cases, at least one histological feature of neurocytoma was found; and more importantly, the tumor cells were positive for neuronal markers including synaptophysin and NSE, which confirmed that the tumors were neurocytoma outside the CNS." (PMID 26376790, 2015). "Considering the differentia diagnosis against clear cell ependymomas and oligodendrogliomas, neuropil-like islands and diffuse synaptophysin and NeuN positivity are in favor of neurocytoma." (PMID 26376790, 2015). "On the other hand, expression of the neuronal marker synaptophysin is observed in nearly all patients with central neurocytomas but rarely found in oligodendrogliomas." (PMID 24877104, 2014). "In addition, synaptophysin immunoreactivity is a typical finding for central neurocytomas, which are also clear cell-type tumors." (PMID 24744929, 2014). "The lack of synaptophysin positivity makes a diagnosis of neurocytoma unlikely." (PMID 25755903, 2015).
prostate tumors (10 papers, 2013 to 2024). "The immunostaining analysis reveals high levels of the αVβ3 integrin which correlate with SYP expression in the prostate tumors and lung metastatic lesions of DKO and TKO mice (n = 5 for each group)." (PMID 33481853, 2021). "NE phenotype prostate tumor cells in TRAMP mice display similar morphological and molecular characteristics to human NED and NEPC cells, including the expression of IHC markers, synaptophysin, chromogranin A and FOXA2, and loss of expression of cytokeratin 8 (CK8)." (PMID 23620793, 2013). "All metastases resembled primary prostate tumors and showed high levels of CK8 and SYP coexpression along with nearly undetectable expression of nuclear AR." (PMID 36928314, 2023). "Immunostaining of prostate tumour sections demonstrated expression of glyceraldehyde-3-phosphate dehydrogenase (GAPDH), recoverin, alpha-enolase and synaptophysin in NET cells." (PMID 28382556, 2017). "To better understand this mechanism we investigated the co-expression of Brachyury with chromogranin A (CHGA) and synaptophysin (SYP) in silico, two NEtD markers described to distinguish prostate tumors with NE features." (PMID 27049720, 2016). "Immunohistochemical stains of the primary prostate tumor demonstrated positive staining of the AR, NKX3.1, and PSMA, and negative staining for neuroendocrine (NE) markers synaptophysin, chromogranin A, and DLL3." (PMID 34385567, 2021). "Indeed, prostate tumors were small or absent in DKO-Nicd1 mice, failed to express NE markers such as SYP, and were composed primarily of lower-grade adenocarcinoma or intraductal neoplasia." (PMID 39024561, 2024).
adenoma (9 papers, 2009 to 2024). A neoplasm arising from the epithelium. "Tumor #1 was composed of 90% adenoma tissue; it was densely granulated, stained positively for prolactin and synaptophysin and negatively for other adenohypophyseal hormones, and presented a proliferation index (MIB-1) < 1%." (PMID 39876960, 2024). "The distinction of SCO from an oncocytic variant of a pituitary adenoma is based on the expression of neurosecretory markers synaptophysin and chromogranin by the adenoma." (PMID 21320334, 2011). "Positive immunohistochemical staining for neuroendocirne tissue, NSE, chromogranin, and/or synaptophysin suggest that adenoma of the temporal bone originates from neuroectoderm." (PMID 20111612, 2009). "Transdifferentiation of adenoma cells into neurons is yet to be established, but adenoma cells are known to express some neuronal epitopes, particularly synaptophysin, and may, therefore, have the potential to transdifferentiate." (PMID 32706866, 2020). "Furthermore, metanephric adenomas lack immunoreactivity for neuroendocrine markers such as synaptophysin, chromogranin, and CD56." (PMID 26445413, 2015).